FGFR3 (fibroblast growth factor receptor 3)
Diseases named in the same sentence as FGFR3 in open-access papers (continued):
Sharing a sentence is not in itself a finding about the gene and the disease.
metastatic disease (5 papers, 2014 to 2026). "FGFR3 copy number gain and loss were rare events in primary and metastatic tumors (0.8% each; 3.0% and 12.3%, respectively)." (PMID 24846059, 2014). "FGFR3 prevalence varied significantly by disease stage, study design, and region, with higher rates in advanced/metastatic disease and randomized trials (p < 0.05)." (PMID 42278538, 2026). "Of 14 paired primary and metastatic tumors, three pairs were positive for FGFR3 staining, whereas seven pairs were negative for FGFR3 staining." (PMID 24846059, 2014). "The presence or absence of FGFR3 IHC staining does not appear to have an impact on OS in patients with metastatic disease who are treated with platinum-based chemotherapy." (PMID 24846059, 2014). "In metastatic tumor specimens (N = 31), FGFR3 staining did not correlate with OS (HR = 1.12, 95% CI [0.49–2.58], P = 0.78)." (PMID 24846059, 2014).
neuroepithelial tumors (5 papers, 2018 to 2025). "FGFR2 or FGFR3 gene fusions are also a characteristic molecular feature of a recently described subtype of low grade neuroepithelial tumour—Polymorphous Low-grade Neuroepithelial Tumour of the Young (PLNTY)." (PMID 37130917, 2023). "Further studies have found that there are frequent genetic abnormalities involving B-Raf proto-oncogene (BRAF) or fibroblast growth factor receptors 2 and 3 (FGFR2, FGFR3), which can induce the occurrence and development of neuroepithelial tumors." (PMID 33363022, 2020).
Osteopenia (5 papers, 2015 to 2025). Osteopenia is a term to define bone density that is not normal but also not as low as osteoporosis. "Either FGFR3 deficiency or constitutive activation results in osteopenia and disrupts the mineralization of bone, accompanied by altered osteoclastic activity." (PMID 40256430, 2025). "Adult Fgfr3-deficient mice displayed osteopenia, indicating that Fgfr3 also participates in osteoblast differentiation." (PMID 38956429, 2024). "Duplan's study discovered that the activation of FGFR3 in hypertrophic chondrocytes and immature osteoblasts (Osx-Fgfr3) in mice not only disturbed the hypertrophic cells in the growth plate, impacting the growth of long bones but also caused osteopenia and decreased cortical thickness at adulthood." (PMID 40256430, 2025). "To determine whether the osteopenia and cranial vault defects observed in adult Osx-Fgfr3 mice were caused by impaired OB proliferation, differentiation and/or activity, we cultured OBs generated from calvaria of Osx-cre and Osx-Fgfr3 mice in vitro." (PMID 33737326, 2021). "In contrast, marked osteopenia was present in adult (3-month-old) Osx-Fgfr3 mice compared with Osx-cre mice." (PMID 33737326, 2021). "Along with defective long bone elongation, adult Osx-Fgfr3 mice also displayed marked osteopenia, as shown by the low trabecular bone volume and low cortical thickness." (PMID 33737326, 2021). "Additional studies in skeletally mature FGFR3−/− mice revealed osteopenia arising from defective osteoblast mineralization." (PMID 25852647, 2015). "However, inactivation of Fgfr3 in mice showed osteopenia, reduced cortical thickness, and an increased number of osteoclasts." (PMID 37345656, 2023). "Given the osteopenia, low cortical thickness and membranous craniofacial defects observed in adult Osx-Fgfr3 mice and the impaired mineralization by OBs observed in vitro, we conclude that OBs are indeed affected by Fgfr3 overactivation and contribute to bone modifications independently of CCs." (PMID 33737326, 2021). "Total deletion of Fgfr3 results in osteopenia and thinner cortical bone in adult mice, and the absence of Fgfr3 increases early OB differentiation but interferes with the cells' normal activity, thus leading to defective mineralization." (PMID 33737326, 2021). "In contrast, we did not observe osteopenia in growing Osx-Fgfr3 mice at the age of 3 weeks, suggesting that the low bone mass observed at 3 months is independent of growth plate anomalies and is due (at least in part) to defective bone remodeling, rather than poor bone mass gain." (PMID 33737326, 2021). "We found that Fgfr3 activation in immature OBs and hypertrophic CCs not only perturbed hypertrophic cells in the growth plate (thus affecting long bone growth) but also led to osteopenia in adult (3-month-old) mice but not in growing (3-week-old mice)." (PMID 33737326, 2021).
rhabdomyosarcoma (5 papers, 2009 to 2025). A rare aggressive malignant mesenchymal neoplasm arising from skeletal muscle. "For instance, implantation of a single FGFR3-positive KYM-1 rhabdomyosarcoma cell can form a tumor nodule in vivo consisting of histologically defined rhabdomyosarcoma cells, whereas a single FGFR3-negative cell cannot form such nodules." (PMID 24467821, 2014). "Because FGFR3-positive rhabdomyosarcoma cells, including KYM-1 cells, were characterized as RSCs in our previous study, it was not necessary to repeat this characterization in this study." (PMID 24467821, 2014). "To develop a novel and innovative therapy against malignant rhabdomyosarcoma, we previously identified rhabdomyosarcoma stem cells (RSCs) and showed that fibroblast growth factor receptor 3 (FGFR3) is a marker of RSCs." (PMID 24467821, 2014). "In other soft tissue tumors such as synovial carcinomas or rhabdomyosarcomas, FGFR3 was involved in the malignant phenotype." (PMID 23902722, 2013). "Rhabdomyosarcoma cell lines included small populations of fibroblast growth factor receptor 3 (FGFR3)-positive cells." (PMID 19888223, 2009). "Our findings suggest that rhabdomyosarcoma cell lines include a minor subpopulation of FGFR3-positive sarcoma-initiating cells, which can be maintained indefinitely in culture and which is crucial for their malignancy." (PMID 19888223, 2009). "We found that human rhabdomyosarcoma cell lines include a small proportion of fibroblast growth factor receptor 3 (FGFR3)-positive cells." (PMID 19888223, 2009). "Real-time PCR revealed that FGFR3 was upregulated in embyonal rhabdomyosarcoma patient biopsy specimens." (PMID 19888223, 2009). "Likewise, the careful analyses in our previous study characterized FGFR3-positive rhabdomyosarcoma cells as RSCs." (PMID 24467821, 2014). "Inhibition of FGFR3 signalling or activation of CNTF signalling might thus be a good candidate for anti-cancer stem cell therapy for rhabdomyosarcoma." (PMID 19888223, 2009). "To determine whether the subset defined by FGFR3 was enriched for RICs, we compared the abilities of FGFR3+ and FGFR3− rhabdomyosarcoma cells to initiate tumour formation in vivo." (PMID 19888223, 2009). "In our study, RICs were enriched in rhabdomyosarcoma subpopulations defined by FGFR3 alone." (PMID 19888223, 2009). "Immunohistochemical examination revealed that a portion of rhabdomyosarcoma cells expressed FGFR3." (PMID 19888223, 2009). "The intensity of FGFR3 expression differed among rhabdomyosarcoma cells." (PMID 19888223, 2009). "In summary, we identified FGFR3-positive RICs in human rhabdomyosarcoma cell lines." (PMID 19888223, 2009). "We found that three rhabdomyosarcoma cell lines, KYM-1, RD, and A204, each included a small proportion of FGFR3-positive cells (1.6–2.6%)." (PMID 19888223, 2009). "Although RICs are enriched in the rhabdomyosarcoma subpopulations defined by FGFR3, not every FGFR3+ cell is an RIC, as 67% of purified single RICs did not form tumours." (PMID 19888223, 2009).
sarcoma (5 papers, 2009 to 2025). A usually aggressive malignant neoplasm of the soft tissue or bone. "For FGFR 3 the IIIC/IIIB ratios were even higher (12.2 ± 5.5 for the normal adrenal glands and adrenocortical adenomas vs. 11.9 ± 7.7 for the ACC samples vs. 11.7 ± 3.2 for ACC cell-lines) similar again to the mesenchymal sarcomas (9.1 ± 7.1)." (PMID 33917436, 2021).
short-limbed dwarfism (5 papers, 2009 to 2025). "TD is a lethal form of short-limbed dwarfism caused by mutations of FGFR3, which lead to constitutive activation of FGFR3 tyrosine kinase activity." (PMID 39023844, 2025). "Hypochondroplasia is the most common type of short-limb dwarfism in children resulting from fibroblast growth factor receptor 3 (FGFR3) mutation." (PMID 25505998, 2014).
triple-negative breast carcinoma (5 papers, 2020 to 2025). An invasive breast carcinoma which is negative for expression of estrogen receptor (ER), progesterone receptor (PR), and human epidermal growth factor receptor 2 (HER2). "FGFR3 activation promotes PARP inhibitor resistance in triple negative breast cancer, which can be reversed by the combination of FGFR inhibitors and PARP inhibitors." (PMID 40460005, 2025). "We identified a high prevalence of activated FGF receptor 3 (FGFR3) in BRCAm triple-negative breast cancer (TNBC) cells with intrinsic and acquired PARPi resistance." (PMID 40460005, 2025). "In triple negative breast cancer, aberrant FGFR3 activation was identified through the mass spectrometry (MS)-based tyrosine phosphorylation profiling." (PMID 38635549, 2024).
campomelic dysplasia (4 papers, 2018 to 2026). "The other sample harboring an FGFR3 mutation (F11077-1) had an initial DH of campomelic dysplasia, with unspecific ultrasound findings (short bent bones, brachycephaly, and narrow thorax)." (PMID 30043834, 2018).
cardiac hypertrophy (4 papers, 2016 to 2023). "Functional experiments have shown that FGFR3 is highly expressed in primary cardiomyocytes and regulates the intracellular calcium levels and cardiac contractility in cardiac hypertrophy, suggesting that it plays a role in cardiomyocytes or heart development." (PMID 35518361, 2022). "To obtain further insight into potential FGFR-mediated signalling mechanisms in TAC-induced cardiac hypertrophy, we investigated mRNA expression of Fgfr1, Fgfr3 and Fgfr4 in WT, VDRΔ/Δ, Fgf23−/−/VDRΔ/Δ, and Klotho−/−/VDRΔ/Δ mice, 4 weeks after TAC." (PMID 28900153, 2017). "Furthermore, we used AAV9 vectors carrying short hairpin RNA (shRNA) (AAV9-cTNT-sh-FGFR3) to silence FGFR3 in cardiomyocytes specifically to evaluate the impact of FGFR3 on cardiac hypertrophy." (PMID 36871047, 2023). "However, the role of FGFR3 in cardiac hypertrophy and heart failure is unknown and needs further investigation." (PMID 26914935, 2016). "Mechanistic studies indicate that FGF18/FGFR3 promote FYN activity and expression and negatively regulate NADPH oxidase 4 (NOX4), thereby inhibiting reactive oxygen species (ROS) generation and alleviating pathological cardiac hypertrophy." (PMID 36871047, 2023). "Consistently, silencing of FGFR3 did not affect myocardial hypertrophy." (PMID 36871047, 2023).
Cognitive impairment (4 papers, 2021 to 2024). Abnormal cognition is characterized by deficits in thinking, reasoning, or remembering. "Taken together, these data show that downregulating neuronal FGFR3 decreases tau uptake and neurotoxic tau pathology, thereby preventing neuronal cell death and restoring cognitive impairments in AD model mice." (PMID 38951140, 2024). "We observed that FGFR3 knockdown in ADLPAPT mice restored cognitive deficits in three different behavioral tests, consistent with prior studies." (PMID 38951140, 2024). "Garcia-Hafner-Happle syndrome, also known as fibroblast growth factor receptor 3 (FGFR3)-ENS, is characterized by a systematized keratinocytic EN of soft and velvety type with neurological abnormalities such as seizures, intellectual impairment, and cortical atrophy." (PMID 34438587, 2021).
depression (4 papers, 2013 to 2025). "The FGFR3 gene, encoding a member of the fibroblast growth factor receptor family, has been reported to be exclusively expressed in the locus coeruleus in patients with major depressive disorder." (PMID 32830860, 2020). "Carnosic acid has a tendency to reduce FGF9 expression in post-stroke depression rats, while also reversing the relationship between FGF9 and FGFR-3, and reducing infarct volume in PSD rats." (PMID 40458804, 2025). "Alterations of astrocyte-enriched fibroblast growth factor (FGF) receptors observed here (upregulation of Fgfr3, downregulation of Fgfr1) may also be relevant to depression biology given the findings of altered expression of FGF receptors and ligands in depression." (PMID 23966905, 2013).
Ewing sarcoma (4 papers, 2005 to 2025). A small round cell tumor that lacks morphologic, immunohistochemical, and electron microscopic evidence of neuroectodermal differentiation. "This included FGFR1 amplification in RMS (n = 3), Ewing sarcoma (ES; n = 2), OS (n = 1) and a sarcoma other (n = 1); FGFR3 amplification in a CNS tumour (n = 1); and FGFR4 amplification in RMS (n = 3)." (PMID 37130917, 2023). "In order to identify the receptor(s) that transduces the inhibitory FGF2 signal in Ewing tumour cells, Western blot analyses identified FGFR1, -2 protein in all cell lines, whereas FGFR-3 protein was only detected in TC-71, VH-64 and WE-68." (PMID 15685229, 2005).
Insulin resistance (4 papers, 2012 to 2025). Increased resistance towards insulin, that is, diminished effectiveness of insulin in reducing blood glucose levels. "FGFR3 mutations primarily affect bone growth, but the same molecular mechanisms—dysregulated FGFR3 signaling and downstream pathways—can also stimulate epidermal proliferation, distinguishing it from insulin resistance–associated AN." (PMID 40384885, 2025). "Interestingly, FGFR3 expression in scWAT was also negatively correlated with HOMA-IR (homeostasis model assessment of insulin resistance) and fasting plasma insulin concentrations." (PMID 32184391, 2020). "Liraglutide treatment markedly improved insulin resistance and increased FGF-21 expression in liver and FGFR-3 in adipose tissue, restored β-Klotho mRNA expression in adipose tissue as well as FGFR-1-3, β-Klotho levels and phosphorylation of FGFR1 up to the levels observed in control mice in liver." (PMID 23152772, 2012).
leukemia (4 papers, 2020 to 2022). A malignant (clonal) hematologic disorder, involving hematopoietic stem cells and characterized by the presence of primitive or atypical myeloid or lymphoid cells in the bone marrow and the blood. "Here, we identified that the loss of FGFR3 reprograms MLL-AF9 (MA)-driven murine AML cells into weakly pathogenic CD117-positive leukemia stem-like cells by activating the FGFR1-ERG signaling pathway." (PMID 33584313, 2020). "We also found that FGFR3-deficient leukemia cells were weakly pathogenic due to the downregulation of chemokines genes." (PMID 33584313, 2020). "NTRK1 and FGFR3 are HDAC class I-associated genes in leukemia and NB patients and cell lines." (PMID 34944663, 2021). "FGFR3-deficient leukemia cells are weakly pathogenic because of downregulation of chemokines genes." (PMID 33584313, 2020). "Indeed, FGFR3 mutants with reduced capacity for PLCγ activation strongly attenuated, but not abolished, transformative capacity in Ba/F3 cells and in a bone marrow murine leukemia transplant model, underling the importance of PLCγ for oncogenesis downstream of FGFR3." (PMID 33494394, 2021). "More importantly, only NTRK1 and FGFR3 were detected to be high-scoring among both leukemia and NB patients and cell lines." (PMID 34944663, 2021). "Firstly, we surprisingly found that CD117-positive leukemia stem-like cells (GFP+CD117+CD11b+/low) have a 20-fold higher percentage in MA-induced FGFR3-knockout leukemia cells (MA-KO) than in MA-induced WT leukemia cells (MA-WT)." (PMID 33584313, 2020). "In summary, our studies showed that FGFR3 negatively regulates the generation of CD117+ leukemia stem-like cells by activating FGFR1-ERG-CD117 signaling." (PMID 33584313, 2020). "We found that FGFR3 deletion reprogrammed MA-AML cells into CD117+ leukemia stem-like cells by activating the FGFR1-ERG-CD117 signaling pathway." (PMID 33584313, 2020). "Through the analysis of transcriptomic data of 701 leukemia and NB patient samples and cell lines, we revealed that the expression of RTK, such as KIT, FLT3, AXL, FGFR3, and NTRK1, is linked with HDAC class I. Although HDAC inhibitors have antitumor activity, they also have high whole-body toxicity." (PMID 34944663, 2021). "Inhibition of FGFR3 will be a promising approach for clinical leukemia therapy." (PMID 33584313, 2020). "However, CD117+ FGFR3-deficient leukemia cells are not real LSCs because of a defect of FGFR3 downstream signaling and gene expression." (PMID 33584313, 2020). "Here we firstly found that FGFR3 had a novel regulatory mechanism for the stemness of LSCs in AML, and provided a promising anti-leukemia approach by interrupting FGFR3." (PMID 33584313, 2020). "We measured the expression of genes coding RTKs: FLT3, KIT exclusively in leukemia cell lines, PDGFRa, AXL in NB, NTRK1, FGFR3, INSR, ROR2, and RET in both NB and leukemia cells by qRT-PCR, which were top-scoring RTK-coding genes among leukemia and NB cell lines." (PMID 34944663, 2021). "Our findings showed that FGFR3 deletion programs leukemia cells (non-LSCs) into CD117+ leukemia stem-like cells." (PMID 33584313, 2020). "Extraordinarily, we found that FGFR3 mediates a novel reprogramming mechanism by which leukemia cells (non-LSCs) could be converted into CD117+ leukemia stem-like cells." (PMID 33584313, 2020).
lymph node metastasis (4 papers, 2019 to 2023). "Increased FGFR3 expression enhanced the recurrence risk (hazard ratio 4.72, p = 0.029), while high FGFR4 expression was associated with lymph node metastasis (p = 0.036)." (PMID 36142417, 2022). "Furthermore, our study shows that the increased tumor mRNA expression of FGFR3 is an unfavorable prognostic factor in terms of the risk of recurrence for Sq-NSCLC patients and the increased FGFR4 mRNA level is correlated with lymph node metastasis occurrence." (PMID 36142417, 2022). "FGFR3 gene amplification was detected in lymph node metastasis." (PMID 34692530, 2021). "FGFR3, which is highly expressed in CMM tissues, is correlated with increased Breslow thickness and lymph node metastasis." (PMID 31619201, 2019). "FGFR3 expression in CMM tissues was correlated with Breslow thickness and lymph node metastasis." (PMID 31619201, 2019).
meningioma (4 papers, 2016 to 2025). A generally slow growing tumor attached to the dura mater. "Clinical trials for sqNSCLC with the selective FGFR1-4 inhibitor erdafitinib are currently ongoing (NCT03827850), and a favorable therapeutic outcome is predicted in FGFR3-mutated meningiomas." (PMID 31565188, 2019). "Thus, FGFR3 mutations may be a prognostic biomarker for a favorable outcome in meningioma patients, who may further respond to erdafitinib treatment." (PMID 31565188, 2019). "Among the meningiomas, the most common mutations were in NF2 (59/71), PIK3CA (22/71), FGFR3 (13/71), SMO (11/71) and AKT1 (10/71), with Tertp (1/71) mutations the least frequent." (PMID 31565188, 2019). "Fibroblast growth factor receptor-3 was found to induce the proliferation of meningioma cells via activation of the phosphoinositide 3 kinase-Akt-PRAS40-mTOR and STAT3 pathways." (PMID 27895530, 2016). "Importantly, FGFR2 and FGFR3 were detected in meningiomas, and FGF1 was shown to be able to stimulate meningioma cell proliferation by activation of AKT1 and STAT3." (PMID 35996584, 2022). "The macrophages in meningioma had one drug-target kinase that was significantly increased in expression compared to VS (FLT3), whereas VS had two drug-target kinases, FGFR2 and FGFR3." (PMID 41437121, 2025).